MEF2C (myocyte enhancer factor 2C)
Diseases named in the same sentence as MEF2C in open-access papers (continued):
Sharing a sentence is not in itself a finding about the gene and the disease.
amyotrophic lateral sclerosis (2 papers, 2017 to 2024). Amyotrophic lateral sclerosis (ALS) is a neurodegenerative disease characterized by progressive muscular paralysis reflecting degeneration of motor neurons in the primary motor cortex, corticospinal tracts, brainstem and spinal cord. "A recent investigation demonstrated that an amyotrophic lateral sclerosis (ALS)-associated SNP located in the intronic region of MEF2C (rs304152), residing in a putative enhancer element, causes neuronal mitochondrial dysfunction." (PMID 39259737, 2024). "A recent study showed a significant up-regulation of MEF2C and MEF2D mRNA levels in both sporadic and SOD1+ amyotrophic lateral sclerosis (ALS) patients detected by gene expression analysis, and a down-regulation of their targets, BDNF, KLF6, and RUFY3." (PMID 29340119, 2017).
Autoimmunity (2 papers, 2008 to 2022). The occurrence of an immune reaction against the organism's own cells or tissues. "Neither Mef2c, Grap2, or Plekha was previously linked to tolerance or autoimmunity." (PMID 19578517, 2008). "Of note, IRF4, MEF2C, and SPI1 have been reported to be crucial in the development of autoimmunity." (PMID 35350715, 2022).
cardiomyopathy (2 papers, 2009 to 2014). A disease of the heart muscle or myocardium proper. "Considering the important role of SRF and MEF2C in the progression of cardiomyopathy, a subnetwork under their regulation was constructed and the biological functions they may affect were also indicated." (PMID 25338953, 2014). "A subnetwork under the regulation of SRF and MEF2C was also constructed and the functions they may affect were also indicated considering the considerable evidence in support of their involvement in cardiomyopathy." (PMID 25338953, 2014). "Finally, forced expressions of either MEF2C or PGC-1α are known to lead to mitochondrial ultrastructural abnormalities and development of cardiomyopathy." (PMID 20041152, 2009).
colitis (2 papers, 2023). Inflammation of the colon. "Mef2c promoted M1 macrophage polarization by directly activating the transcription of Il2a and Il12b, facilitating resistance to Listeria monocytogenes infection and susceptibility to colitis." (PMID 37733446, 2023).
Duchenne muscular dystrophy (2 papers, 2021 to 2023). Duchenne muscular dystrophy (DMD) is a neuromuscular disease characterized by rapidly progressive muscle weakness and wasting due to degeneration of skeletal, smooth and cardiac muscle. "The muscle-specific lncRNA (linc-MD1) associate with Duchenne muscular dystrophy (DMD) to control the expression of transcriptional factors mastermind-like protein 1 (MAML1) and MEF2C." (PMID 33568070, 2021).
fragile X syndrome (2 papers, 2021 to 2022). A genetic syndrome caused by mutations in the FMR1 gene which is responsible for the expression of the fragile X mental retardation 1 protein. "For instance, the transcription factor myocyte enhancer factor 2c (MEF2c), which is associated with fragile X syndrome, has been clearly identified as a negative regulator of synapse number in the mouse brain." (PMID 34360985, 2021).
Hepatic fibrosis (2 papers, 2019 to 2023). The presence of excessive fibrous connective tissue in the liver. "MEF2C was reported to regulate the activation of hepatic stellate cells and play a key role in hepatic fibrosis, a pathological response to live injury." (PMID 33430979, 2019). "Furthermore, MEF2C directly activates SPTBN1 and consequently induces liver fibrosis." (PMID 36814339, 2023).
hypertrophic cardiomyopathy (2 papers, 2016 to 2021). A condition in which the myocardium is hypertrophied without an obvious cause. "Interestingly, genetic variations at the 5’UTR of Mef2C that promote Mef2C transcription are associated with hypertrophic cardiomyopathy." (PMID 27901468, 2016). "Among these candidates, MEF2C was interesting in the present study owing to the crucial involvement of MEF2C in heart development, cardiomyocyte reprogramming and hypertrophic cardiomyopathy." (PMID 33817315, 2021).
invasive ductal carcinoma (2 papers, 2012 to 2021). "For instance, MEF2C was identified as a candidate gene/molecular marker for the transition from ductal carcinoma in situ (DCIS) to invasive ductal carcinoma (IDC) and evaluated by RT-PCR." (PMID 22952604, 2012).
leishmaniasis (2 papers, 2022 to 2024). Infectious disease that is transmitted through the bite of hematophagous female phlebotomine sand flies. "Mef2c has been demonstrated to be associated with enrichment of classical activated macrophages that promote pro-inflammatory cytokine production in leishmaniasis." (PMID 38299832, 2024).
lupus (2 papers, 2020 to 2022). "Indeed, most Nr4a1-controlling genes (Grin1, Creb3l3, Mef2a, Mef2c, and Mef2d) were reduced in the lupus hippocampus, as revealed by sequencing assays." (PMID 35177587, 2022).
mesothelioma (2 papers, 2023 to 2025). A usually malignant and aggressive neoplasm of the mesothelium which is often associated with exposure to asbestos. "Using transcriptomic data from these models, we identified MEF2C and MYOCD as upstream regulators of the invasive mesothelioma model." (PMID 37146029, 2023).
myotonic dystrophies (2 papers, 2019 to 2025). "Dysregulation of MEF2c isoforms has been identified in muscle disorders that resemble in some traits LGMDD2, such as myotonic dystrophies (DM1 and DM2)." (PMID 41291251, 2025).
ventricular septal defect (2 papers, 2018 to 2023). The presence of a defect (opening) in the septum that separates the two ventricles of the heart. "A study found the ucRNA, T-uc.167, which is located on the antisense chain of the coding gene Mef2c, exhibits high expression in patients with ventricular septal defect (VSD)." (PMID 37036543, 2023).
Arrhythmia (1 paper, 2017). Any cardiac rhythm other than the normal sinus rhythm. "This gene however resides in a highly conserved region that includes the miRNA miR-92, and myocyte enhancer factor 2c (MEF2C) gene, a myocardial transcription factor whose protein levels are associated with arrhythmias in mice." (PMID 28464817, 2017).
Arthritis (1 paper, 2021). Inflammation of a joint. "Inducible deletion of Mef2c in mice resulted in increased bone mass under physiological conditions and protected mice from bone erosion by diminishing osteoclast formation in K/BxN serum induced arthritis, a murine model of inflammatory arthritis." (PMID 33424022, 2021).
B cell lymphoma (1 paper, 2022). "Mutations in MEF2C are often found in patients with B cell lymphoma, and these mutations are involved in the pathogenesis of abnormal B cell proliferation." (PMID 35092700, 2022).
B-cell acute lymphoblastic leukemia (1 paper, 2022). A neoplasm of lymphoblasts committed to the B-cell lineage, typically composed of small to medium-sized blast cells. "Specifically, SS18 rearrangements involving the MEF2C and MEF2D partner genes, resulting in MEF2C::SS18 and MEF2D:SS18 gene fusions, have been identified in microsecretory adenocarcinoma and the B‐cell acute lymphoblastic leukemia, respectively." (PMID 35639915, 2022).
behavioral disorders (1 paper, 2020). "The neurosynaptic injury resulting from the lncRNA11496/Mef2c/HDAC2 pathway could serve as a new mechanism of mental and behavioral disorders induced by T. gondii." (PMID 32499679, 2020).
bladder cancer (1 paper, 2016). "Also, the MEF2C, miR-145 and JPX correlated with the survival of bladder cancer patients (P=0.026)." (PMID 27322142, 2016).
Brain atrophy (1 paper, 2018). Partial or complete wasting (loss) of brain tissue that was once present. "Collectively, findings from our and other studies indicate that MEF2C and HDAC9 may participate in a pathway leading to NFT formation and brain atrophy." (PMID 29458411, 2018).
breast tumour (1 paper, 2021). "Finally, a study detected miR-223-3p in exosomes released by IL-4 (interleukin-4)-activated macrophages; this miRNA has been shown to transfer to breast tumour cells where it regulates invasion through the Mef2c (myocyte enhancer factor 2C)-β-catenin pathway." (PMID 34064331, 2021).
centronuclear myopathy (1 paper, 2009). Centronuclear myopathy (CNM) is an inherited neuromuscular disorder characterized by clinical features of a congenital myopathy and centrally placed nuclei on muscle biopsy. "It has been reported that MEF2C directly activates the expression of a muscle specific protein kinase Srpk3 and Srpk3-null mice exhibit widespread centronuclear myopathy via an unknown mechanism." (PMID 19400950, 2009).
Cerebral atrophy (1 paper, 2015). Atrophy (wasting, decrease in size of cells or tissue) affecting the cerebrum. "Expression of the top five differentially expressed genes found by GWAS - MS4A6A, CD2AP, INPP5D, MEF2C and CLU – all have good correlation with Braak stage and cerebral atrophy." (PMID 26202100, 2015).
chronic myeloid leukemia (1 paper, 2025). "In chronic myeloid leukemia, repression of miR-223 results in the activation of MEF2C and its downregulation negatively correlates with disease risk." (PMID 39695050, 2025).
chronic periodontitis (1 paper, 2021). A chronic inflammatory process that affects the tissues that surround and support the teeth. "Myocyte-specific enhancer factor 2C (MEF2C) was identified as a critical transcription factor involved in the coexpression network of chronic periodontitis." (PMID 33869630, 2021). "Three transcription factors, FOS, MEF2C, and USF2, were identified as related to the regulation of the crosstalk genes and were also found to be dysregulated in chronic periodontitis." (PMID 33869630, 2021).
colon adenocarcinoma (1 paper, 2023). "In cancer, Mef2c plays oncogenic roles in various types, including ALL, AML, colon adenocarcinoma, lymphomas, prostate, and hepatic cancers." (PMID 38110859, 2023).
Dandy-Walker syndrome (1 paper, 2019). "Of those subjects with available results, one had Dandy Walker Syndrome, one had Wiedemann Steiner Syndrome, one had a 15q13.3 microdeletion, one had 21q22.2 deletion, and one had MEF2C and PIK3C2G gene variants." (PMID 31780970, 2019).
dysplasia (1 paper, 2023). A usually neoplastic transformation of the cell, associated with altered architectural tissue patterns. "The target genes of many miRNAs can express transcription factors and are associated with cardiac dysplasia and apoptosis, such as Nkx2.5, Zeb2, Mef2c, and Ets1." (PMID 38053046, 2023).
Dystonia (1 paper, 2025). An abnormally increased muscular tone that causes fixed abnormal postures. "Interestingly, Mef2c-KD mice exhibited dystonia-like phenotype and reduction of hindlimb and forelimb muscle strength." (PMID 39920775, 2025).
embryonal rhabdomyosarcoma (1 paper, 2022). A poorly circumscribed morphologic variant of rhabdomyosarcoma. "In embryonal rhabdomyosarcoma, Notch signaling promotes a self-renewal program in tumor propagating cells by inducing SNAIL1, which strongly represses MEF2C." (PMID 35536646, 2022).
Friedreich ataxia (1 paper, 2022). An inherited condition that affects the nervous system and causes movement problems. "Furthermore, thousands of drugs have been tested on neurons from patients with Friedreich’s ataxia on the reactivation of the silenced Fmr1 gene, Niemann–Pick disease type C on lysosomal cholesterol accumulation, and PD on MEF2C activity." (PMID 35163606, 2022).
hyperhomocysteinemia (1 paper, 2017). A serious metabolic condition caused by mutations in the MTHFR gene, medications, or nutritional deficiency. "Hydrogen sulfide (H2S) can mitigate hypertrophy via reversal of expression of miR-133a through activation of MEF2C in hyperhomocysteinemia cardiomyocytes." (PMID 29340119, 2017). "In hyperhomocysteinemia induced cardiac hypertrophy, the downregulation and inactivation of MEF2C leads to attenuation of expression of miR-133a, an anti-hypertrophic factor in cardiomyocytes." (PMID 29340119, 2017).
hyperlipidemia (1 paper, 2024). "Our study highlights the pathogenic role of CflarR splicing mediated by neuronal Mef2c, which aggravates neuron necroptosis following stroke with comorbid hyperlipidemia and proposes CflarR splicing as a potential therapeutic target for hyperlipidemic stroke patients." (PMID 39648651, 2024). "Our results reveal that Mef2c‐regulated alternative Cflar splicing would be a potent neuroprotective target for stroke patients with hyperlipidemia." (PMID 39648651, 2024). "In this study, we reported that hyperlipidemia exacerbated ischemic brain injury after stroke, and highlighted the novel functions of Mef2c in modulating alternative splicing of Cflar to further aggravate neuron necroptosis in HFD‐treated MCAO mice." (PMID 39648651, 2024). "We found that hyperlipidemia promoted alternative splicing of CflarR via upregulating Mef2c expression in ischemic neurons, thus aggravated neuron necroptosis and neurological deficits following ischemic stroke." (PMID 39648651, 2024). "Our findings reveal a novel mechanism of how hyperlipidemia comorbidity exacerbates ischemic brain injury after stroke and identify neuronal CflarR splicing regulated by Mef2c as a new therapeutic target for neuroprotection of stroke patients with hyperlipidemia." (PMID 39648651, 2024).
ischemia (1 paper, 2015). A hypoperfusion of the BLOOD through an organ or tissue caused by a PATHOLOGIC CONSTRICTION or obstruction of its BLOOD VESSELS, or an absence of BLOOD CIRCULATION. "In addition, MEF2C level is found to increase in the activated microglia around the hippocampus after ischemia." (PMID 25890150, 2015).
ischemic stroke (1 paper, 2024). A stroke disorder caused by obstruction of blood flow to the brain, due to thrombotic (local blood clot formation) or embolic (due to a blood clot or other material traveling from another site) event. "Sexual difference exists in the pathophysiology of ischemic stroke, therefore, future studies on the role of Mef2c should also include female mice." (PMID 39648651, 2024).
keloid (1 paper, 2022). An irregularly shaped, elevated mark on the skin caused by deposits of excessive amounts of collagen during wound healing. "In terms of expression level, BMP4, MSX1, TBX2, SIX1, DLX5, and DLX2 were lowly expressed, while HAND2, IRX1, EDN1, and MEF2C were highly expressed in keloid fibroblasts." (PMID 35047146, 2022).
language delay (1 paper, 2021). "A 122,226bp deletion in MEF2C, affecting the full protein coding region of the gene, was found in a child (ID 09) with language delay, abnormal MRI and EEG findings, and seizure onset at 26 months." (PMID 34469436, 2021).
leiomyosarcoma (1 paper, 2017). An uncommon, aggressive malignant smooth muscle neoplasm, usually occurring in post-menopausal women. "Master regulators of Oncopig leiomyosarcomas were also consistent with human leiomysoarcomas, including MEF2C, which acts as a tumor suppressor in human leiomyosarcoma." (PMID 28879168, 2017).
Leukoencephalopathy (1 paper, 2023). This term describes abnormality of the white matter of the cerebrum resulting from damage to the myelin sheaths of nerve cells. "To determine how the neuronal MEF2C transcription network is affected by IFN-I hyperactivation, we examined a published snRNA-seq dataset of RNaseT2−/− mice, a model of infantile-onset RNaseT2-deficient leukoencephalopathy with severe IFN-I neuroinflammation and cognitive impairment." (PMID 37095396, 2023).
Lewy body disease (1 paper, 2021). "In fact, MEF2C has been reported to be association with clinico-pathological features of Lewy body disease." (PMID 34386032, 2021).
liver diseases (1 paper, 2017). "Accordingly, Mef2c and Gadd45b, corresponding to lncRNA 2900097C17Rik, may be involved in liver diseases in a bacterial or viral response-like manner." (PMID 29383134, 2017).
lymphoid tumors (1 paper, 2022). "By means of a T-lineage–specific conditional knockin MEF2Ctg/tg/Lck-Cre mouse model, we provide evidence that prolonged MEF2C expression is pathogenic during early T cell development in the thymus that leads to biphenotypic lymphoid tumors." (PMID 35536646, 2022). "Aging MEF2C/Lck-Cre mice developed lymphoid tumors in various organs including the thymus and lymph node areas in 3 of 9 mice at 2 years of age." (PMID 35536646, 2022).
macular degeneration (1 paper, 2016). Loss of vision in the central portion of the retina (macula), secondary to retinal degeneration. "MEF2C was also reported to be associated with retinal vascular caliber in the Cohorts for Heart and Ageing Research in Genomic Epidemiology (CHARGE) consortium, which is particularly interesting given the known role of VEGF in proliferative retinopathy and macular degeneration." (PMID 26910538, 2016).
memory impairment (1 paper, 2025). "More importantly, TH deficiency-induced PV+ interneuron reduction could substantially contribute to cognitive and memory impairment in offspring via Maf-mediated downregulation of Mef2c expression." (PMID 40564155, 2025).
motor neuron disease (1 paper, 2025). "Altogether, the motor behavior tests demonstrated motor neuron disease-like behaviors in both upper and lower motor neurons Mef2c-deficient mice." (PMID 39920775, 2025). "Together, this study proves that the noncoding variant of MEF2C, rs304152, is a bona fide risk factor of motor neuron disease, and provides an insight on how a noncoding genetic mutation drives epigenetic changes in the pathogenesis of motor neuron disease." (PMID 39920775, 2025).
Myocardial fibrosis (1 paper, 2009). "The data indicate that depletion of MEF2C is sufficient to markedly attenuate the hypertrophic growth and myocardial fibrosis of overloaded left ventricle by a mechanism dependent on defective activation of mTOR/S6K pathway." (PMID 20041152, 2009).
myocardial ischemia (1 paper, 2020). A disorder of cardiac function caused by insufficient blood flow to the muscle tissue of the heart. "It was elucidated that MEF2C alleviated myocardial ischemia by reducing coagulation." (PMID 32960786, 2020).
myotonic dystrophy type 1 (1 paper, 2019). Steinert disease, also known as myotonic dystrophy type 1, is a muscle disease characterized by myotonia and by multiorgan damage that combines various degrees of muscle weakness, arrhythmia and/or cardiac conduction disorders, cataract, endocrine damage, sleep disorders and baldness. "Dysregulated expression of several miRNAs and mRNAs in a myotonic dystrophy type 1 (DM1) cell model, was rescued with the exogenous addition of MEF-2C." (PMID 31105874, 2019).
osteopetrosis (1 paper, 2023). Osteopetrosis, also known as marble bone disease, is a descriptive term that refers to a group of rare, heritable disorders of the skeleton characterized by increased bone density on radiographs. "Bone resorption studies have exhibited that the reduced expression of MEF2C contributes to osteopetrosis and the dysregulation of pathological bone remodeling." (PMID 37628864, 2023).
Phelan-McDermid syndrome (1 paper, 2015). A rare genetic neurodevelopmental disorder characterized by neonatal hypotonia, global developmental delay, normal to accelerated growth, absent to severely delayed speech, and minor dysmorphic features. "In contrast to contiguous gene syndromes such as Williams syndrome, several other microdeletion syndromes have been shown recently to be caused mainly by haploinsufficiency of a single responsible gene such as MEF2C in 5q14.3 microdeletion syndrome or SHANK3 in Phelan-McDermid syndrome." (PMID 26421060, 2015).
pleural tumours (1 paper, 2023). "Invasive pleural tumours were characterised by a transcriptomic signature enriched for genes associated with MEF2C and MYOCD signaling, muscle differentiation and myogenesis." (PMID 37146029, 2023).